IL1B (interleukin 1 beta)
Diseases named in the same sentence as IL1B in open-access papers (continued):
Sharing a sentence is not in itself a finding about the gene and the disease.
cardiac hypertrophy (continued). "Although the effect of IL-1β on angiotensin II-dependent cardiac hypertrophy is unknown, data from clinical settings and experiments have indicated that IL-22-IL-22R1-IL-10R2 binding can regulate IL-6, IL-17, IL-1β, TNF-α, and IFN-γ expression." (PMID 29358851, 2017). "The present study found that CTX produced massive change including cardiac hypertrophy, fibrosis, heart edema with inflammatory cell infiltration and the expression change of several cytokines such as IL-1β, TNF-α and promoting IL-10, which were antagonized by BAE." (PMID 26133371, 2015). "Cas-1 cut leads to the cleavage of downstream cytokines pro-Interleukin-1 beta (pro-IL-1β) and pro-Interleukin-18 (pro-IL-18) into their mature forms IL-1β, IL-18, thereby inducing cardiomyocyte damage and subsequently resulting in myocardial hypertrophy, fibrosis, and impaired cardiac function." (PMID 40242439, 2025). "Moreover, although it is recently found that caspase-1 is activated in mice after aortic banding and regulates angiotensin II-induced cardiac hypertrophy by cleavage of IL-1β, whether caspase-1 plays a role in HP requires further investigation." (PMID 33842546, 2021). "Caspase‐1 and IL‐1β expression levels are significantly up‐regulated in hypertrophic cardiomyocytes both in vivo and in vitro, and the inhibition of caspase‐1 can mitigate cardiac hypertrophy induced by angiotensin II, which offers a therapeutic potential against cardiac hypertrophy." (PMID 30525268, 2019). "Afterintervention with the macrophage depleting agent Liposome encapsulated clodronate(LEC), the degree of myocardial hypertrophy and fibrosis decreased, and theexpression of TGF-β1, TNF-α1, and IL-1β decreased." (PMID 39076555, 2024). "Previous studies have demonstrated the important roles of interferon-gamma (IFN-γ), tumor necrosis factor-α (TNF-α), interleukin-1beta (IL-1β), and IL6 in cardiac hypertrophy and dysfunction." (PMID 37554327, 2023). "TLR2/NF-κB/IL-1β signaling is essential for activating the IGF-1/PI3K/Akt pathway and leads to adaptive cardiac hypertrophy during pressure overload." (PMID 37113698, 2023). "In the development of cardiac hypertrophy, the increased expression of IL-6, TNF-α, and IL-1β is closely related to Collagen I and Collagen III deposition." (PMID 36270989, 2022). "The release of inflammatory cytokines such as TNF-α, IL-1β, IL-6, and IL-8, and the production of inducible nitric oxide synthase (iNOS) and cyclooxygenase-2 (COX-2), can lead to cardiac hypertrophy and impaired cardiac function." (PMID 35276939, 2022). "Antibiotics reduced the HW/BW ratio, cardiac hypertrophy/fibrosis, and the level of TLR4 and IL-1β in the ileum, and rescued the muscularis layer thickening, villus length, and numbers of Paneth and goblet cells in the ileum of HSD-ANP−/− mice." (PMID 35956306, 2022). "The expression and activation of pro-inflammatory cytokines, such as IL-1β, IL-6, IL-8, and TNF-α are involved in myocardial fibrosis, myocardial hypertrophy, oxidative stress-related injury, and cardiac dysfunction." (PMID 34997266, 2022). "The JAK/STAT pathway also transduces signals for a wide array of cytokines and growth factors including ANGII, TNF-α, IL-1β, IL-6 and IFN-γ, all of which have been involved in cardiac hypertrophy." (PMID 34225646, 2021). "Previous investigations have shown that the IL-1β and NLRP3 inflammasomes are involved in cardiac hypertrophy." (PMID 34168567, 2021). "One investigation showed that IL-1β and the NLRP3 inflammasome play an important role in pressure overload-induced cardiac hypertrophy in mice." (PMID 34168567, 2021). "We established in vivo and in vitro models of cardiac hypertrophy via TAC and Ang-II treatment, respectively, and observed a significant increase in pyroptotic cells, along with upregulation in IL-1β, cleaved caspase-1, and GSDMD-N." (PMID 33723236, 2021).
cardiac hypertrophy (continued). "UUO resulted in cardiac hypertrophy, accompanied by an elongation of the QRS wave on the ECG, decreased expression of Cxcl1, Cxcl9, and Il1b, reduced the number of CD11b+ cells, and increased in titin isoform parameters, such as T1/MHC and TT/MHC ratios, without changes in fibrosis markers." (PMID 40869420, 2025). "Pressure overload-induced cardiac hypertrophy in mice was found to increase myocardial IL-6 and IL-1β levels, although TNFα levels were not affected." (PMID 38256155, 2024). "We found that neutralizing IL-1β in Acsl4 TG mice significantly reduced TAC-induced cardiac hypertrophy, improved cardiac systolic performance, prevented cardiomyocyte hypertrophy, and reduced all three markers of cardiac hypertrophy." (PMID 39327446, 2024). "IL-1-β decreases the expression of SERCA (sarcoplasmic reticulum calcium ATPase), and phospholamban (PLB), which can induce diastolic dysfunction, while IL-18 induces fibrosis and cardiac hypertrophy resulting in diastolic stiffness and concentric remodeling." (PMID 36837434, 2023). "Interestingly, nanoceria significantly diminished the expression of genes related to cardiac hypertrophy (BNP, ANP, and β-MHC) and pro-inflammatory signaling (IL-1β, TNF-α, and iNOS) in H9c2 cells." (PMID 37107252, 2023). "Proinflammatory cytokines, including IL-6, IL-1β, IFN-γ, IL-17, and TNF-α, could induce cardiac hypertrophy, fibrosis, and apoptosis and further induce inflammation, ultimately resulting in HF." (PMID 35669500, 2022). "After the gene was knocked out, it reduced cardiac-related inflammatory factors such as IL-6 and IL-1β, TNF-α and so on, which may be mainly through NF-κB and MAPK signaling pathways to regulate the production of myocardial hypertrophy." (PMID 36064568, 2022). "Furthermore, suppressing IL-1β and the inflammasome pathway ameliorates transverse aortic constriction (TAC) -induced ventricular hypertrophy." (PMID 34168567, 2021). "Notably, suppressing IL-1β and NLRP3 inflammasome pathways ameliorates TAC -induced ventricular hypertrophy in mice." (PMID 34168567, 2021). "Additionally, stretching cardiac fibroblasts was observed to induce low levels of IL-1β secretion; although these levels were insufficient to induce IL-6 production, these were enough to stimulate insulin-like growth factor-1 (IGF-1) for the induction of cardiac hypertrophy." (PMID 38256155, 2024). "Moreover, we found that the expression of Il1b and Nlrp3 (which encode the cytokine IL-1β and the pyrin-like protein NLR family pyrin domain containing 3, respectively) were significantly upregulated in TAC-induced cardiac hypertrophy in Acsl4 F/F mice, but not in Acsl4 KO mice." (PMID 39327446, 2024). "The expression levels of cardiac hypertrophy markers (ANP, BNP, and β-MHC) and inflammatory factors (IL-1β and IL-6) increased in the model, the mir-30b-5p-non-loaded, and the mir-30b-5p-loaded groups (p < 0.05)." (PMID 34658880, 2021). "TLR4 inhibition within the PVN attenuated MAP, improved cardiac hypertrophy, reduced TNF-α, IL-1β, iNOS levels, and NFκB activity in SHR but not in WKY rats." (PMID 25879545, 2015). "However, compared with the model and mir-30b-5p-non-loaded NPs, the expression of cardiac hypertrophy markers (ANP, BNP, and β-MHC) and inflammatory factors (IL-1β, IL-6) were significantly decreased (p < 0.05)." (PMID 34658880, 2021).
cerebral infarction (68 papers, 2011 to 2025). An ischemic condition of the brain, producing a persistent focal neurological deficit in the area of distribution of the cerebral arteries. "For IL-1β −511C/T polymorphism, there were 3271 cerebral infarction cases and 3619 controls from 13 articles." (PMID 27679860, 2016). "The inhibition of iNOS, TNF-α, and IL-1β mRNA expression is one of the mechanisms underlying the neuroprotective effects of Caf against cerebral infarction." (PMID 27703487, 2016). "The effects of IL-1β in brain injury have also been linked to promotion granulocytosis that can drive neuronal cell death, induction glutamatergic neurotoxicity, and reduction in cerebral blood flow to exacerbate brain infarction." (PMID 33183330, 2020). "IL-1β and IL-1β antibodies have been reported to reduce cerebral edema and cerebral infarction in the mouse MCAO model." (PMID 40831534, 2025). "Studies indicate that puerarin treatment in tMCAO rats decreases cerebral infarction volume, enhances neural function, and lowers pro‐inflammatory factors IL‐1β, IL‐6, and TNF‐α, likely via CAP activation." (PMID 40715012, 2025). "M1 microglia (with TNF-α or CD86 as markers) generate pro-inflammatory factors, such as TNF-α, IL-1β, IL-6, and interferon-γ, which promote inflammation and exacerbate I/R injury and cerebral infarction." (PMID 39391701, 2024). "An increased expression of pro-inflammatory cytokines such as IL-1β has been widely studied and linked to cerebral infarction with the NLRP3 inflammasome and its inflammatory pathways (including caspase-1 and IL-1β)." (PMID 36676165, 2023). "The decreasing effect of therapeutic hypothermia on the Il1β expression has been prior shown in various clinical setting, like cerebral infarction or renal reperfusion injury." (PMID 37123355, 2023). "Inflammatory factors TNF-α, IL-6, and IL-1β participate in the process of early inflammatory injury of cerebral infarction." (PMID 36936654, 2023). "In MCAO rats, miR-29b overexpression reduced brain infarct volume and brain edema, decreasing IL-1β levels in leukocytes and in the brain 24 hours poststroke." (PMID 36052307, 2022). "The results revealed that expressions of the IL-1β and IL-18 proteins increased in the cerebral infarction cortex of MCAO rats." (PMID 33820869, 2021). "MiR-17-5p mimic administration ameliorated TXNIP expression, NLRP3 inflammasome activation, caspase-1 cleavage, and IL-1β production, as well as brain infarct volume." (PMID 29394934, 2018). "Previous studies showed that administration of rhIL-1β enhances ischemic brain edema formation, size of the brain infarction, increases neuronal death, whereas, administration of anti–IL-1β reverses the neuronal death in rat model." (PMID 22727020, 2012). "Previously published studies have demonstrated that elevated CSF and plasma levels of IL-1β correlate with larger brain infarcts and worse functional outcome." (PMID 21450100, 2011). "Overexpression of IL-1β increases the incidence of cerebral infarction and induces pro-inflammatory mediators including leukotrienes and platelet activation factors, while blockage of IL-1β attenuates ischemic brain injury and alleviates neutrophil infiltration in MCAO injury." (PMID 38527023, 2024). "SHJKSmex is presumed to inhibit the increase in IL-1β and thus reduce the cerebral infarct size." (PMID 34184969, 2021). "SFN treatment of rats with middle cerebral artery occlusion inhibited the activation of inflammatory vesicles and the expressions of caspase-1, IL-1β and IL-18, reduced the volume of cerebral infarction, improved the score of neurological function, and reduced neutrophil infiltration." (PMID 34526897, 2021). "Both NADPH and Apocynin inhibit the expression of NLRP3, ASC, caspase-1, IL-1β, and IL-18 in the ischemic cerebral cortex in a rat cerebral infarction model, and reduce the volume of cerebral infarction, improve survival after infarction, and restore neurological function." (PMID 34526897, 2021).
cerebral infarction (continued). "We did not detect a significant association between IL-1β −511C/T polymorphism and cerebral infarction susceptibility under any genetic models in the random-effect model." (PMID 27679860, 2016). "Our result found that there was no positive relationship between IL-1β +3953C/T polymorphism and cerebral infarction risk in the fixed-effect model as well." (PMID 27679860, 2016). "PF reduces cerebral infarction area by inhibiting NFκB, IL-1β, and TNFα." (PMID 23818926, 2013). "Meanwhile, although we have demonstrated the significance of IL-17A, we also observed reduced levels of IL-1β and CCL2 in the cerebral infarction homogenates of P2X7-KO mice following tMCAO." (PMID 40948793, 2025). "After MDSC depletion, the anti-inflammatory and neuroprotective effects of CGRP in cerebral infarction mice were markedly attenuated, as evidenced by increased expression of TNF-α, IL-1β and IL-6 and elevated neuronal apoptosis." (PMID 40963921, 2025). "Calycosin significantly reduced neurological impairments and brain infarction in a dose-dependent manner, alleviated neuronal damage and decreased the expression of pyroptosis-related markers, including NLRP3, GSDMD, HMGB1, IL-1β, IL-18, and caspase-1." (PMID 40606597, 2025). "Increases the levels of A subunit and B subunit in GABA and IL-1β, IL-6, TNF-α to reduce neurological deficit and cerebral infarct area." (PMID 35548468, 2022). "Geniposide has been shown to significantly reduce the area of cerebral infarction and alleviate neuronal damage and necrosis mainly by inhibiting inflammatory signals, including NLRP3, TNF-α, IL-6, and IL-1β." (PMID 34454545, 2021). "The present study showed that Sino significantly decreased the mRNA levels of pro-inflammatory cytokines, including IL-1β, IL-6, IL-18, and TNF-α, in the tissues surrounding the cerebral infarction." (PMID 27724964, 2016). "In the present study, both SGD and clopidogrel inhibited the inflammatory response arising from cerebral infarct and our results demonstrated unequivocally that SGD was a more potent inhibitor of the expression of IL-1β, TNF-α, and MCP-1 than clopidogrel." (PMID 27413737, 2016). "Clausen and collaborators demonstrated that IL-1β mRNA and TNF-α mRNA, and TNF-α protein are produced by CD11b+ microglia/macrophages in the penumbra as well as the core of brain infarction." (PMID 22082476, 2011). "During the acute phase of cerebral infarction, blood–brain barrier damage and endothelial cell degeneration occur in patients with acute ischemic stroke (AIS), accompanied by elevated levels of TNF-α and IL-1β." (PMID 40260140, 2025). "Studies have shown that Genipin could significantly reduce the area of cerebral infarction and attenuate neuronal damage and necrosis by inhibiting inflammatory factors such as NLRP3, TNF-α, IL-6, and IL-1β." (PMID 39679371, 2024). "Compared with the model group, AST-IV significantly reduced the neurological function deficit score, cerebral infarct volume, and the protein levels of NLRP3, Caspase-1, pro-IL-1β, IL-1β, pro-IL-18, and IL-18 in brain tissue, and inhibited the expression of phosphorylated NF-κB protein." (PMID 38601463, 2024). "Sal B improved neurological dysfunction, reduced the size of cerebral infarcts and cerebral edema, and inhibited the inflammatory response following cerebral I/R injury by downregulating TLR4, p‐p38MAPK, p‐JNK, nuclear NF‐κB, and IL‐1β production." (PMID 37904689, 2023). "In the acute phase of cerebral I/R injury, SP600125 treatment reduced cerebral infarction by inhibiting the expression of inflammatory mediators including TNF-α, IL-1β, IL-6, and matrix metalloproteinase-9 and downregulating the mitochondria-mediated apoptotic pathway in the ischemic area." (PMID 34419138, 2021).
cerebral infarction (continued). "Neuroprotective parameters such as brain infarction, blood–brain barrier disruption, oxidative stress, TNF-α, and IL-1β mRNA expression, along with apoptotic caspase 3 activity, and with neuroprotective, anti-oxidative, anti-inflammatory, and anti-apoptotic effects of quercetin, were reported." (PMID 34206761, 2021). "Additionally, outcomes included neurological deficit score, brain edema, cerebral infarction area, neuronal apoptosis, serum levels of inflammatory factors (TNF-α, IL-6, and IL-1β), and the antioxidant level of body (SOD, MDA, and GSH-Px)." (PMID 30581490, 2018). "Hydroxysafflor yellow A, a major active component of C. tinctorius L. (Hong Hua), reduces cerebral infarction by suppressing cytosolic NF-κBp65 translocation to the nucleus and subsequently downregulates NF-κB-mediated TNF-α, IL-1β, and IL-6 expression in the ischemic area 24 h after permanent MCAo." (PMID 27703487, 2016). "EA at LU5, LI4, SP6 and ST36 could decrease the score of neurological deficit, reduce the volume of cerebral infarction and improve the degree of nerve cell injury, and inhibit NLRP3, pro-caspase-1, cleaved-caspase-1 p20, pro-IL-1β, cleaved-IL-1β and GSDMD protein expression." (PMID 36925735, 2023). "Results showed that EA could reduce the score of neurological deficit, reduce the volume of cerebral infarction and improve the degree of nerve cell injury, and inhibit NLRP3, pro-caspase-1, cleaved caspase-1 p20, pro-IL-1β, cleaved IL-1β, and GSDMD protein expression." (PMID 35600074, 2022).